CHCHD2 (coiled-coil-helix-coiled-coil-helix domain containing 2)
Diseases named in the same sentence as CHCHD2 in open-access papers (continued):
Sharing a sentence is not in itself a finding about the gene and the disease.
cancer (14 papers, 2014 to 2025). A tumor composed of atypical neoplastic, often pleomorphic cells that invade other tissues. "Based on the 5’UTR mutations, CHCHD2 was classified as a high-priority cancer driver." (PMID 34900699, 2021). "CHCHD2 over expression has been implicated in diverse cancers." (PMID 33537311, 2020). "Previously, the gene expression of human CHCHD2 has been determined by transcriptome analysis to be increased in certain types of cancer tissue compared with that in normal tissues, suggesting that CHCHD2 may be associated with the progression of cancer." (PMID 25625293, 2015). "In particular, there is a report that mitochondrial CHCHD2 interacts with Bcl-xL to inhibit mitochondrial apoptosis in a cancer cell line model." (PMID 38214772, 2024). "We were surprised that CHCHD2 loss favored survival under diverse culture stresses in hESCs because CHCHD2 was previously determined to inhibit apoptosis through direct BCL-xL interaction in cancer cell lines." (PMID 38214772, 2024). "Some of the genes specifically mutated in noncoding regions were identified as highly potent cancer drivers, of which BAD had a mutation hotspot in the 3’UTR, DHODH had a mutation hotspot in the Kozak sequence in the 5’UTR, and CHCHD2 frequently showed mutations in the 5’UTR." (PMID 34900699, 2021). "Previously, human CHCHD2 gene was determined overexpression in some of cancer tissues." (PMID 32054470, 2020). "Thus, future studies may be warranted on the specific role of CHCHD2 in cancer stem cell metabolism." (PMID 25415228, 2014). "Mitochondrial CHCHD2, initially identified as a mitochondrial chaperone protein binding partner, inhibits apoptosis through BCL-xL interaction in cancer cell models and regulates mitochondrial morphology in Drosophila models." (PMID 38214772, 2024). "In lean NASH-HCC, methylation differences were seen in genes involved with cancer progression and prognosis (including HCC), such as CHCHD2, FSCN1, and ZDHHC12, and lipid metabolism, including PNPLA6 and LDLRAP1." (PMID 36474183, 2022). "But we found S100A7, CHCHD2 and SQSTM1 directly interacted with Akt that plays a vital role in signalling pathway of cancer cells." (PMID 24991204, 2014). "Unlike cancer cells, where ROCK activity governs actin organization to promote cell migration, the level of CHCHD2 expression gave only marginal effect on migration capacity." (PMID 38214772, 2024). "Unlike previous cancer cell line studies demonstrating that mitochondrial CHCHD2 interacts with BCL-xL to inhibit apoptosis, CHCHD2 KO in hESCs inhibited mitochondrial cell death induced by genotoxic insults, which was re-sensitized by CHCHD2 reconstitution." (PMID 38214772, 2024).
tumor (10 papers, 2010 to 2025). "However, further in vitro and in vivo studies are needed to elucidate molecular mechanism underlying the role of CHCHD2 in tumor angiogenesis." (PMID 31839816, 2019). "The analysis demonstrated significantly higher CHCHD2 mRNA expression in primary tumours compared to normal tissues in both the GSE53819 NPC data set and the TCGA HNSCC data set." (PMID 40434251, 2025). "In our study, hellebrigenin significantly reduced the tumour volume in the NPC xenograft model, and Ki67 and CHCHD2 expression were reduced in hellebrigenin‐treated tumours." (PMID 40434251, 2025). "The same study also elucidated the relation between tumor size and CHCHD2 expression, staging, and survival rate." (PMID 33537311, 2020). "CHCHD2 expression was significantly related with smoking, tumor size, differentiation degree, TNM Stage, lymph metastasis (all P<0.05)." (PMID 32054470, 2020). "Eight genes centromeric to SEPT14 (ZNF713, MRPS17, GBAS, PSPH, CCT6A, SUMF2, PHKG1 and CHCHD2) were amplified in tumour 4 only." (PMID 21170331, 2010). "Additionally, CHCHD2 knockdown led to down regulation of CD105 which is a noted marker for angiogenesis which now exposes the role of CHCHD2 in tumor angiogenesis." (PMID 33537311, 2020). "Subsequently, we found that the expression of CHCHD2 in NSCLC was notably associated with some clinical parameters of NSCLC, such as smoking (P = 0.045), tumor size (P = 0.000), differentiation degree (P = 0.034), TNM stage (P = 0.000), lymph metastasis (P = 0.000)." (PMID 32054470, 2020). "In conclusion, CHCHD2 may play an oncogenic role in HCC via promoting tumor cell growth and migration while preventing apoptosis." (PMID 31839816, 2019). "The results showed that the mRNA and protein expression levels of CHCHD2 and HIF-1a in tumor tissues were significantly higher than those in the normal tissues." (PMID 32054470, 2020). "Additionally, CHCHD2 mRNA expression was higher in advanced stages of HNSCC than in earlier stages, with a similar trend observed for tumour size." (PMID 40434251, 2025). "In vivo studies demonstrated that hellebrigenin suppressed the tumour volume without affecting body weight, accompanied by the downregulation of Ki67 and CHCHD2 expression." (PMID 40434251, 2025). "The results showed that the positive stain of CHCHD2 and HIF-1a were 94.7% (198/209) and 95.7% (200/209) in tumor tissues, there were significantly higher than that in adjacent non-cancerous tissues 11.0% (23/209) and 68.9% (144/209), (P = 0.000, P = 0.000) respectively." (PMID 32054470, 2020). "Immunohistochemical staining for the CHCHD2 biomarker was markedly positive and diffuse throughout the tumor tissue (right) and absent from the adjacent normal liver tissue (left)." (PMID 25625293, 2015). "CHCHD2 was highly expressed in the HCC specimens and was consistent with tumor markers of HCC." (PMID 25625293, 2015). "In addition, we detected the protein expressions of CHCHD2 and HIF-1a in tumor tissues and adjacent non-cancerous tissues by immunohistochemistry in specimens from 209 patients." (PMID 32054470, 2020).
genetic diseases (1 paper, 2021). "The emergence of altered CHCHD2 expression in a variety of gene mutations responsible for dissimilar genetic diseases raises the red flag that such changes in gene expression may represent some stochastic and disease-unrelated epigenetic event associated with reprogramming and/or subcloning." (PMID 34660586, 2021).
neurological diseases (1 paper, 2022). "Mutations in CHCHD2 and CHCHD10 can lead to neurological diseases, while CHCHD2 and CHCHD10 are degraded by proteases under stress conditions." (PMID 35173147, 2022).
CHCHD2 also shares sentences with these, for which no sentence is quoted: Parkinsonism (6 papers); frontotemporal lobe dementia (4); Autoimmunity (2); glioblastoma (2); invasive ductal carcinoma (2); Lissencephaly (2); lung adenocarcinoma (2); mitochondrial disease (2); bacterial sepsis (1); benign breast disease (1); cardiomyopathy (1); Charcot-Marie-Tooth disease type 1A (1); cognitive disorder (1); follicular carcinoma of the thyroid (1); glioma (1); Insulin resistance (1); leukemia (1); liver (1); Lung Squamous Cell Carcinoma (1); lymphoma (1); MELAS (1); metastatic disease (1); Mohr-Tranebjaerg syndrome (1); motor neuron disorder (1); myopathy (1); nonalcoholic steatohepatitis (1); tauopathy (1).